LEP (leptin)
Diseases named in the same sentence as LEP in open-access papers (continued):
Sharing a sentence is not in itself a finding about the gene and the disease.
Obesity (continued). "Excess nutrients, which can result from consuming a high-fat diet, rapidly reduce hypothalamic responses to exogenously administered leptin and induce dietary obesity." (PMID 40690443, 2025). "A recent study showed that the upregulation of spliced X-box binding protein 1 (Xbp1s) in AGRP neurons reverses diet-induced obesity and improves leptin and insulin resistance." (PMID 40531768, 2025). "Parabacteroidetes negatively correlated with leptin concentrations, which aligns with published research, where these bacteria alleviate obesity and obesity-related dysfunctions in mice." (PMID 40649705, 2025). "Leptin is a hormone that helps control appetite, insulin levels, and obesity by acting on the hypothalamus." (PMID 40871683, 2025). "Perinatal leptin intake has been shown to protect against obesity, and against the MONW phenotype in adult rats." (PMID 40944384, 2025). "Leptin also activates feedback pathways that restrain LepRb signaling in the face of high leptin, as in obesity." (PMID 40393800, 2025). "Mutations in LEP, LEPR, POMC, and MC4R disrupt this regulatory loop, resulting in hyperphagia, reduced satiety, and early-onset obesity." (PMID 40281302, 2025). "High levels of leptin, which are common in individuals with obesity due to leptin resistance, fail to properly signal satiety, leading to continued food intake and reduced energy expenditure." (PMID 40016558, 2025). "Hyperleptinemia-induced leptin resistance can contribute to obesity by disrupting hypothalamic satiety signaling." (PMID 41141252, 2025). "Adipocyte-derived leptin resistance in obesity blunts estrogen’s anorexigenic effects while impairing gonadotropin-releasing hormone (GnRH) pulsatility, thereby decoupling metabolic status from reproductive readiness." (PMID 40343364, 2025). "Additionally, obesity comes with a chronic state of inflammation, which can be attributed to altered adipocytokine homeostasis; excess adipose tissue is associated with lower levels of adiponectin, which has anti-inflammatory properties, and higher leptin levels, which promote inflammation." (PMID 40364176, 2025). "A phase 1 RCT in which adults with common obesity or overweight together with low baseline leptin levels (<5 ng/mL) were treated with mibavademab, demonstrated a placebo-subtracted weight loss of -2.8 kg (-3.1%) and -2.4 kg (-3.1%) in a phase 1 RCT." (PMID 39929239, 2025). "Clinical studies must stratify participants by obesity phenotypes, leptin resistance status, metabolic comorbidities, and genetic risk factors such as APOE-ε4 to assess context-dependent adipokine effects." (PMID 41155642, 2025). "Leptin, a hormone produced by adipocytes, has a prominent role in satiety behavior, with increased levels leading to leptin resistance in obesity and metabolic syndromes." (PMID 40443710, 2025). "Protein Tyrosine Phosphatase 1B (PTP1B) is a negative regulator of leptin signaling whose disruption protects against diet-induced obesity in mice." (PMID 39149290, 2025). "Leptin, an adipokine elevated in patients with obesity, plays an important role in energy homeostasis." (PMID 41463012, 2025). "The role of leptin in the obesity–Pso connection has been underscored by several studies, which have consistently reported elevated leptin expression and circulating levels in patients with Pso compared to controls." (PMID 40893809, 2025). "Further research is needed to clarify the relationship between leptin levels and lipid profiles in diabetic patients, particularly those with obesity." (PMID 41239622, 2025). "People with obesity had higher leptin concentrations (p=0.03, and p<0.01), lower adiponectin/leptin (p=0.03 and p<0.01), and higher leptin/resistin ratios (p=0.09 and p<0.01) in both AT and serum respectively." (PMID 40352457, 2025). "Oishi and Hashimoto (2018) showed that nighttime feeding (day feeding in nocturnal mice) led to the development of leptin resistance, resulting in obesity and metabolic disease." (PMID 40649840, 2025).
Obesity (continued). "In boys, the relationship between leptin and puberty is more complex and less clearly understood; however, boys with obesity enter puberty at a later age." (PMID 40564637, 2025). "In particular, obesity, insulin resistance, and metabolic syndrome were all strongly predicted by a high leptin-adiponectin ratio." (PMID 40642705, 2025). "Oishi and Hashimoto (2018) revealed that time-restricted feeding, when implemented during the resting phase, leads to leptin resistance, thereby promoting obesity and metabolic disorders." (PMID 40649840, 2025). "GDM and obesity are responsible for the development of a chronic inflammatory state that involves the hyperproduction of proinflammatory cytokines and leptin, while there is reduced production of adiponectin." (PMID 41007128, 2025). "There are studies suggesting a gene-gene interaction between the LEP and LEPR variants in a genetic susceptibility to the development of obesity." (PMID 40152811, 2025). "Leptin, an adipokine produced by adipocytes, acts in opposition to adiponectin and is crucial in the development of insulin resistance, obesity, and diabetes." (PMID 41048434, 2025). "One such model is ob/ob mice, which lack the adipokine leptin and, as a result, develop hyperphagia, severe obesity, and MASLD." (PMID 39752519, 2025). "Previous studies have shown that elevated palmitic acid concentrations in the brain promote obesity and obesity-related metabolic disorders by impairing hypothalamic leptin signaling." (PMID 40690443, 2025). "A variety of obesity-related hormones, including leptin, adiponectin, insulin/insulin-like growth factor (IGF) family members, and sex hormones, have been identified in recent studies, as contributing to the colon carcinogenesis and poor prognosis of CRC." (PMID 40406485, 2025). "In obesity, hypothalamic neurons develop leptin resistance while ChP transport remains intact, chronically exposing microglia to elevated leptin." (PMID 41516046, 2025). "There is also evidence that obesity impairs the effects of leptin, leading to resistance that also involves its receptor’s function, LEP-R." (PMID 41227378, 2025). "Multiple regulatory factors within neuroendocrine pathways, including leptin, ghrelin, and galanin, are involved in both obesity and pain modulation." (PMID 41343605, 2025). "We should also note a growing field of human milk composition science, which has identified obesity- and diabetes-related biomarkers (leptin, insulin, and glucose) as predictors of breastfeeding cessation among mothers with obesity." (PMID 40691947, 2025). "Of particular note, inflammatory markers leptin and hs-CRP showed strong positive associations with CIMT (p < 0.001), underscoring the role of chronic low-grade inflammation in obesity-induced endothelial dysfunction." (PMID 40940402, 2025). "Hypoadiponectinemia and hyperleptinemia are observed in both adults and children with obesity, and the adiponectin/leptin ratio has been suggested as a sensitive marker for metabolic syndrome in children and adolescents." (PMID 40282897, 2025). "Obesity is a potent inducer of puberty, with increased leptin levels at the pre-pubertal period and increased bone age due to aromatization." (PMID 40095159, 2025). "Obesity-related leptin elevation acts in concert with hypertension-driven Ang II, producing a potent synergistic effect." (PMID 41164182, 2025). "Elevated serum levels of leptin are frequently found in human obesity due to thehormone's degree of influence on hunger, energy consumption, adipose production and insulin function.Serum leptin levels increase with body mass index (BMI) or waist circumference." (PMID 40255297, 2025). "Additional features of EMS include obesity, altered circulating concentrations of adipokines (particularly adiponectin and leptin) and hypertriglyceridaemia." (PMID 38984777, 2025).
Obesity (continued). "Previous studies have demonstrated that HIIT increases adiponectin and lowers the leptin/adiponectin ratio in adolescents with obesity and reduces leptin resistance more effectively than MICT in overweight cancer survivors." (PMID 41367390, 2025). "Leptin and adiponectin influence Aβ metabolism, tau phosphorylation, and neuroinflammation, yet their protective functions are diminished in obesity and metabolic disorders." (PMID 40218960, 2025). "According to a systematic review, aerobic exercise interventions improve fasting insulin levels, insulin resistance, blood lipid levels, LDL, leptin and cortisol levels, and blood visfatin levels in children and adolescents with overweight and obesity." (PMID 40868462, 2025). "Overall, restoring leptin sensitivity through improved delivery methods, combination therapies, or targeting leptin signaling pathways, offers promising strategies for treating obesity, although clinical challenges remain." (PMID 41150735, 2025). "Idalia Cura-Esquivel (2023) states that both obesity and metabolic syndrome are characterized by reduced serum adiponectin levels alongside elevated circulating leptin, leaving room for future studies." (PMID 40282897, 2025). "Patients with obesity had better responses to immunotherapy in different cancers, such as melanoma and NSCLC, which was associated with an elevated leptin level." (PMID 40863244, 2025). "From the discovery of leptin in 1994, I thought that the homeostatic pathway of energy balance was enough to explain obesity." (PMID 40950761, 2025). "Nevertheless, our findings support that leptin replacement with metreleptin is currently the only effective hormonal treatment for this monogenic form of human obesity." (PMID 40415699, 2025). "Maternal high-fat diet also exacerbated obesity in female offspring, accompanied by increased serum leptin levels, decreased insulin sensitivity, destruction of adipose tissue structure, and metabolic and reproductive hormone disorders." (PMID 41220714, 2025). "Ginger oil has been shown to reduce IR, activate the AMPK signaling pathway, increase leptin levels, and reduce blood lipids, which has a positive impact on the prevention and treatment of obesity." (PMID 41199858, 2025). "The observed elevation in serum leptin levels in the HF group is consistent with previous findings that link HF diet-induced obesity to hyperleptinemia and leptin resistance." (PMID 40872133, 2025). "From a mechanistic perspective, in breast cancer tumors associated with obesity, CD8 + T cells bind to leptin and PD-1, resulting in diminished effector functions via STAT3 activation." (PMID 40069732, 2025). "In individuals with obesity, adipose tissue—especially visceral fat—acts as an active endocrine organ that secretes various adipokines (e.g., leptin, resistin, adiponectin), pro-inflammatory cytokines (e.g., TNF-α, IL-6), and chemokines (e.g., MCP-1)." (PMID 41282294, 2025). "Genes implicated in monogenic obesity include POMC, LEP, LEPR, MC3R, and MC4R, while polygenic obesity involves variants in genes such as FTO, UCP1-3, MC4R, ADRB1-3, and SLC6A14." (PMID 41302083, 2025). "In this review, we show, in an updated way, the link between obesity and changes in the signaling pathways of the adipokines leptin, adiponectin, resistin, visfatin, apelin, chemerin, omentin‐1, vaspin, and asprosin in male reproduction." (PMID 40195898, 2025). "Studies established a direct link between the polymorphisms in leptin (LEP) and adiponectin (ADIPOQ) genes, with excessive weight gain and obesity." (PMID 40186666, 2025). "Increased levels of adipokines, such as leptin, in individuals with obesity have been shown to modulate immune function by upregulating pro-inflammatory cytokines and PD-1 expression." (PMID 40227730, 2025). "Dysregulation of adiponectin, resistin, and leptin in obesity and AD establishes a pro-inflammatory and metabolically impaired environment in the brain." (PMID 41155642, 2025).
Obesity (continued). "Key organokines such as fibroblast growth factors FGF19 and FGF21, adiponectin, galectin-3, irisin, and leptin represent well-characterized mediators of inter-organ communication with direct implications in obesity-related metabolic dysfunction." (PMID 40943431, 2025). "Although the hypothalamus is an important regulator of systemic metabolism, excess nutrients can reduce the hypothalamic response to leptin, thereby promoting diet-induced obesity." (PMID 40690443, 2025). "The adipokines adiponectin, leptin, and resistin serve essential functions in the development of obesity and cardiovascular diseases as well as insulin resistance." (PMID 40013194, 2025). "Adipose tissue in obesity releases adipokines (like IL-6, leptin, TNF-α) that sustain systemic inflammation and can alter gut microbiota composition." (PMID 41374093, 2025). "In patients with obesity, leptin levels are elevated, leading to leptin resistance, and the brain is not able to respond to satiety signals." (PMID 41011232, 2025). "Identifying the exact causes of increased obesity risk in DS remains challenging, but contributing factors may include reduced physical activity, unhealthy dietary habits, endocrine disorders, and abnormalities in adipokines, like leptin and adiponectin, commonly described in DS." (PMID 40364270, 2025). "The results of our study provide insights into the relationship between leptin levels and biophysical parameters in type 2 diabetes mellitus patients based on obesity status." (PMID 41239622, 2025). "Inflammatory markers known as CRP, leptin, adiponectin, and the neutrophil/lymphocyte ratio have shown significant correlations with disorders related to obesity." (PMID 40282897, 2025). "However, obesity is associated with leptin resistance and thereby may induce cognitive decline." (PMID 40875171, 2025). "In the context of obesity, it has been shown that elevated leptin levels reflect a dysfunction in its physiological action, which translates into a state of leptin resistance." (PMID 41441006, 2025). "Several factors and mechanisms are involved in the regulation of HDL-cholesterol levels and obesity, high leptin concentrations, and low adiponectin levels are closely related to low HDL-cholesterol levels and quality." (PMID 40416014, 2025). "Diet-induced obesity and leptin administration increase PTPRJ expression in the hypothalamus, and PTPRJ overexpression induces leptin resistance." (PMID 39897330, 2025). "Obesity not only increases the risk of GDM but also exacerbates insulin resistance and chronic inflammation by influencing adipokines (e.g., leptin and adiponectin) secreted by adipose tissue, thereby promoting the onset of GDM." (PMID 41541195, 2025). "PTP1B, in addition to being a potential drug target for treating diabetes and obesity due to its role in downregulating insulin and leptin signalling, has also emerged as a potential therapeutic target for breast cancer treatment." (PMID 41286812, 2025). "Leptin, an adipose-derived hormone that centrally regulates body weight, is elevated in peripheral blood in obesity due to reduced central leptin sensitivity." (PMID 41376865, 2025). "For instance, increased placental production of leptin and alterations in amino acid transporter expression during maternal obesity can enhance fetal growth, contributing to macrosomia and later obesity risks." (PMID 41374021, 2025). "These alterations in leptin, adiponectin, and resistin contribute to improved metabolic profiles and reduced chronic inflammation related to obesity." (PMID 40733199, 2025). "In a maternal Western diet model, leptin supplementation during breastfeeding protected adult offspring from obesity and insulin resistance." (PMID 40290039, 2025). "Our findings echo previous reports in TBI patients and blast-exposed veterans, where chronic leptin elevation was associated with PTSD, obesity, and metabolic syndrome." (PMID 40725107, 2025).
Obesity (continued). "In obesity, elevated leptin levels—resulting from increased adipose tissue—can enhance the secretion of pro-inflammatory cytokines, further activating the JAK/STAT pathway and amplifying inflammatory responses." (PMID 40077690, 2025). "In our study, insulin and leptin levels showed significant improvements in patients with obesity treated with submaximal dosages of GLP-1RA." (PMID 41011232, 2025). "Leptin resistance (LR) is another characteristic feature of obesity, accompanied by elevated serum leptin levels." (PMID 41321496, 2025). "Obesity can lead to leptin resistance, where the brain becomes less responsive to leptin, contributing to overeating and weight gain." (PMID 39780112, 2025). "MSG interrupts leptin-mediated hypothalamus signaling alleyway, triggering the commotion of energy balance and promoting obesity." (PMID 40231296, 2025). "Obesity-related hormones also demonstrated robust group × time effects: leptin (F = 78.011, p < 0.001, ηp2 = 0.796) and adiponectin (F = 68.594, p < 0.001, ηp2 = 0.774), whereas insulin did not (F = 2.291, p = 0.146, ηp2 = 0.103)." (PMID 41367390, 2025). "We found that both GDM and obesity affect placental volume and vascularity, as indicated by reduced leptin and VEGF levels, presumably mediated by epigenetic effects." (PMID 41302116, 2025). "Specific mutations in genes that participate in the leptin-melanocortin pathway, such as those encoding leptin, leptin receptor (LepR), melanocortin-4 receptor (MC4R), and pro-opiomelanocortin (POMC), are recognized to cause monogenic forms of obesity." (PMID 41321496, 2025). "The idea of “leptin resistance,” in which tissues have reduced sensitivity to leptin, was born out of the inability of high leptin levels to address the metabolic imbalance observed in obesity." (PMID 40862144, 2025). "In the context of HFD-induced obesity, leptin’s anorexigenic impact on hypothalamic neurons is diminished, resulting in an increase in appetite and increased fat mass." (PMID 41256259, 2025). "Higher levels of circulating leptin, particularly in the context of obesity, are often indicative of leptin resistance, where the brain and other tissues become less responsive to its signaling, perpetuating an energy imbalance." (PMID 40507170, 2025). "Although leptin has been widely studied as an earlier discovered adipokine, its role in the link between obesity and BC cannot be ignored." (PMID 40414892, 2025). "Individuals with obesity have high circulating leptin due to their increased fat mass, however, and exogenous leptin minimally alters food intake and body weight in most cases of obesity." (PMID 40393800, 2025). "Leptin-induced aldosterone secretion represents a new mechanism driving endothelial dysfunction and cardiac fibrosis in obesity, which disrupts myocardial relaxation and exacerbates CVD." (PMID 40699839, 2025). "Dysregulation of adipokines, such as leptin, a pro‐fibrogenic cytokine, is also responsible for the mechanism of NAFLD caused by obesity." (PMID 41030665, 2025). "The majority of patients with obesity exhibit elevated leptin production, indicating that leptin becomes ineffective in regulating energy balance in this context." (PMID 40607230, 2025). "Conversely, concentrations of leptin are elevated during obesity, leading to leptin resistance, reducing its effectiveness in appetite suppression." (PMID 40034592, 2025). "This study provides relevant evidence on the relationship between gastric and adipose tissue dysfunction in severe obesity and its impact on the ghrelin–leptin hormonal axis, particularly after different types of MBS." (PMID 41441006, 2025). "In obesity and T2DM, leptin also acts as a pro-inflammatory cytokine, causing an inflammatory ripple effect throughout the body." (PMID 40722840, 2025). "Previous scientific research has shown an increased expression of circulating adipokines—leptin and apelin—in obesity-related cancers such as breast cancer and prostate cancer." (PMID 40076482, 2025).